TSG101 (tumor susceptibility 101)
Diseases named in the same sentence as TSG101 in open-access papers (continued):
Sharing a sentence is not in itself a finding about the gene and the disease.
prostate carcinoma (15 papers, 2012 to 2024). A carcinoma that arises from epithelial cells of the prostate gland. "Rather than being deleted, the TSG101 protein is highly expressed in a range of human cancers, typically in association with aberrantly spliced transcripts, and TSG101 splice variants have been identified in leukemia as well as breast, cervical, lung, ovarian and prostate cancers." (PMID 34440370, 2021). "This study also revealed that the levels of HSPA2 in urinary EVs from healthy donors as well as prostate cancer patients were correlated with EVs markers, especially TSG101." (PMID 36959387, 2023). "We further investigated the differences on EV markers CD9, TSG101 and Alix in prostate cancer cell lines and in prostate tissue." (PMID 28881726, 2017). "The EV regulator TSG101 has been reported to play a role in prostate cancer as abnormal transcripts of TSG101 have been identified." (PMID 28881726, 2017). "Interestingly, some EV markers such as ALIX were expressed to a lesser extent in prostate cancer-derived cell lines and EVs when compared to TSG101 or CD9." (PMID 34079007, 2021). "While these reports confirm dynamic interactions between TSG101 and AR, the role of TSG101 in AR signalling may be temporal in prostate cancer." (PMID 28881726, 2017). "Silencing of TSG101 leads to growth arrest and cell death in breast and prostate cancer cells." (PMID 24944680, 2014). "Gene silencing of TSG101 leads to growth arrest and cell death in breast and prostate cancer cells." (PMID 24944680, 2014). "Of note is the presence of several well-known exosomal proteins within the top echelon (i.e. CD9, TSG101, Alix/PDCD6IP) and interestingly, CD9 was increased in prostate cancer samples." (PMID 26196085, 2015). "Western blotting for both TSG101 and PDC6I/Alix demonstrated the successful isolation of exosomes from sera of prostate cancer patients and healthy controls." (PMID 23251413, 2012). "EVs from individuals with prostate cancer typically include cancer-related proteins such as CD9, CD81, and TSG101, as well as Annexin A2, Fatty Acid Synthase (FASN), and a prostate cancer-specific biomarker termed FOLH1 (Prostate Specific Membrane Antigen or PSMA)." (PMID 36059497, 2022). "Manipulation of the AR signalling axis alters the protein cargo in S‐EVs in LNCaP prostate cancer cells, and that the tetraspanin CD9 has been shown to be significantly more abundant in EVs from DHT‐treated cells when comparison with other S‐EVs markers including: TSG101, Alix, CD63 and CD81." (PMID 34434533, 2021). "In contrast, the regulators of MVB-derived exosome biogenesis, TSG101 and Alix, are both found ubiquitously in human prostate adenocarcinoma, with strong expression in the cytoplasm of human prostate cancer specimens, and in the cytosol of LNCaP (data not shown)." (PMID 28881726, 2017).
hepatocellular carcinoma (10 papers, 2013 to 2026). A malignant tumor that arises from hepatocytes. "Namely, TSG101 has been linked with hepatocellular carcinoma, with ovarian cancer and, in Drosophila, a connection has been suggested between TSG101 and neoplasia." (PMID 41227326, 2025). "A recent study suggested that TSG101 promotes the proliferation, migration, and invasion of hepatocellular carcinoma cells by regulating the expression of PEG10 (paternally expressed 10) gene." (PMID 30759747, 2019). "Aberrant splicing and production of TSG101 transcript variations have been detected in multiple types of human cancer, including carcinomas of the liver, lung, breast, cervix, and ovary as well as in soft tissue sarcomas, and leukemias." (PMID 24244542, 2013). "Formerly, TSG101 was considered to be an oncosuppressor; however, thereafter, the content of this protein was found to be increased in various types of cancer, e.g., breast, ovarian, and hepatocellular carcinomas." (PMID 34684727, 2021). "Silencing the expression of TSG101 in Huh7 human hepatocellular carcinoma cells resulted in abnormal actin filaments, growth arrest, and induction of autophagic cell death, which, as reviewed earlier, are similar phenotypic abnormalities that we observed in TSG101 conditional knockout fibroblasts." (PMID 32075127, 2020). "In the presence of TSG101, HK1 is secreted extracellularly via vesicles formed by PM budding and further taken up by hepatocellular carcinoma cells to accelerate hepatocellular carcinoma progression by promoting tumour cell glycolysis." (PMID 38485938, 2024).
lung carcinoma (10 papers, 2014 to 2025). "In accordance with the Minimal Information for Studies of EVs 2024 (MISEV), several known EV markers, including CD9, CD81, Flotillin-1, and TSG101, were observed in the purified serum EVs of patients with lung cancer and healthy individuals." (PMID 41007624, 2025). "Specifically, we showed that lung cancer cells release exosomes with typical exosome markers, such as TSG101, CD81 and calnexin." (PMID 31664930, 2019). "In contrast, TSG101, involved in lung cancer cell proliferation, RAB34, HYOU1 and ACOT1 showed higher expression in AC, as compared to their levels in SCC." (PMID 29285267, 2017). "Other studies described Tsg101 levels to be decreased in different human lung cancer samples; reviewed in." (PMID 24641493, 2014). "In one study, Tsg101 was found to be up-regulated in 15 lung cancer cell lines and five lung cancer tissue specimens." (PMID 24641493, 2014). "Moreover, in our study, EPS15 and the other lung cancer-specific EV markers, GPRC5 and TSG101, were associated with the “negative regulation of the epidermal growth factor receptor” signaling pathway." (PMID 32916986, 2020). "Regarding the expression levels of Tsg101 in lung cancer, different results have been reported." (PMID 24641493, 2014). "Moreover, Tsg101 does promote growth in NIH3T3 fibroblasts as well as in lung cancer cells." (PMID 24641493, 2014). "To further corroborate this effect of syntenin-1 on sEV secretion in lung cancer cells, we evaluated the effect of syntenin-1 on the expression of exosomal marker proteins, such as ALIX, TSG101, and HSP70." (PMID 35136055, 2022). "The abundance of TLN1, TUBA4A, HSPA8, ITGB3, TSG101, and PACSIN2 in the plasma of lung cancer patients was measured using targeted mass spectrometry and compared to that in plasma from healthy volunteers." (PMID 34684727, 2021). "Exosomes derived from lung cancer cells had typical exosome markers, such as CD81, TSG101 and calnexin, which fits with the previously reported protein content for exosomes." (PMID 31664930, 2019).
ovarian carcinoma (9 papers, 2013 to 2025). A malignant neoplasm originating from the surface ovarian epithelium. "Western blot analysis confirmed the presence of exosome-specific protein markers, including CD9, CD63, and tumor susceptibility gene 101 (TSG101), in ovarian cancer (OC) ascites." (PMID 41331197, 2025). "Reduced TSG101 gene products were observed in 36% (8/22) of ovarian cancers and 17% of endometrial cancers." (PMID 38607019, 2024). "In SKOV-3 ovarian cancer cells, the siRNA-mediated knockdown of TSG101 led to a cell cycle arrest at the G2/M phase prior to apoptosis." (PMID 32075127, 2020). "The overexpression of TSG101 was also observed in several human cancers, including ovarian cancer, gastrointestinal tumors and colorectal carcinoma." (PMID 24944680, 2014). "For example, the expression of TSG101 is frequently up‐regulated in human ovarian cancer, colorectal carcinoma, papillary thyroid carcinoma, gastrointestinal tumour, and gallbladder cancer, thus it could be served as a biomarker in several human cancers." (PMID 30450735, 2019). "In ovarian cancer cells, increased TSG101 levels upregulate CBP/p300-interacting transactivator with ED-rich tail 2 (CITED2) and hypoxia-inducible factor 1α (HIF-1α), while downregulating tumor suppressor p21 and subsequently promoting cell growth and survival." (PMID 30759747, 2019). "Similarly, the overexpression of TSG101 has been detected in human papillary thyroid carcinomas, ovarian cancer, gastrointestinal tumors and colorectal carcinoma." (PMID 24944680, 2014). "Our findings thus indicate that TSG101 regulation of p21 is an important factor in the cellular function of TSG101, as has been suggested also by results showing that altered TSG101 expression in ovarian cancer may affect disease prognosis by modulating p21 expression." (PMID 24244542, 2013). "Similarly, the existence of the exosome markers, such as TSG101 and CD63, in the exosome of ovarian cancer patients and normal cases, was validated." (PMID 34690112, 2021).
melanoma (8 papers, 2013 to 2025). A malignant, usually aggressive tumor composed of atypical, neoplastic melanocytes. "The modulation of the CD63 and TSG101 content in sEVs of melanoma cells, as observed by us, was also described as important in promoting the more or less pro-invasive character of secretory vesicles." (PMID 39596498, 2024). "WB analysis of 1 ug total proteins of each fraction demonstrated the enrichment of the exosome-related markers Alix and TSG101 in the iEV fraction, which were barely detectable in the whole melanoma cell lysate." (PMID 35628321, 2022). "The measurement of circulating NK exosomes in the plasma of melanoma patients and healthy donors evidenced lower levels of tsg101+CD56+ exosomes in patients with respect to donors." (PMID 32231660, 2020). "Moreover, exploring the targeting of Rab27 in combination with other proteins involved in sEV secretion, such as TSG101, could additionally improve the therapeutic outcome and become a novel strategy for preventing melanoma progression and metastasis." (PMID 39596498, 2024). "These EVs were enriched with vesicular marker proteins (CD9, CD81 and Tsg101), tyrosinase, F4/80, alpha-smooth muscle actin and E-selectin, suggesting that melanoma cell-, macrophage-, fibroblast- and endothelial cell-derived EVs are present in the melanoma microenvironment." (PMID 26082317, 2013). "Fluctuations in TSG101 and CD63 were also observed in sEVs secreted by the RAB27A knockdown WM164 human melanoma cell line and the RAB27A knockout B16-F10 mouse melanoma cell line; however, this occurred without altering their total number." (PMID 39596498, 2024). "Among the proteins that were found in MVs as well as both exosome subpopulations isolated from melanoma cells, we found suggested EV and exosome marker proteins ALIX, TSG101, CD9, CD81 and CD63, however their relative abundance was higher in LD-Exo and HD-Exo as compared to MVs." (PMID 26931825, 2016).
viral infection (8 papers, 2011 to 2025). "Consistently, the protein levels of ALIX and TSG101 in the VRC were significantly increased by the viral infection." (PMID 38489378, 2024). "The results indicate that ALIX and TSG101 regulate viral infection by inducing host cell-mediated endocytosis and altering viral transport dynamics in the endosome/lysosomal system." (PMID 38489378, 2024). "To assess the involvement of TSG101 in PRRSV life cycle, we tested the effects of TSG101 knockdown on different stages during viral infection." (PMID 35080428, 2022). "More importantly, considering its importance in multiple viral infections, TSG101 is promising to be developed as a broad-spectrum antiviral target." (PMID 35080428, 2022). "Tsg101 UEV domain proteins are potential targets for virus infection therapy, especially for HIV and Ebola viruses." (PMID 32998394, 2020). "Over-expression of Tsg101 significantly shortened the half time by which the virus infection became insensitive to ammonium chloride." (PMID 21931550, 2011). "While depletion of Tsg101 markedly reduced viral infection, over-expression of recombinant Tsg101 significantly accelerated cell entry of LASV and LCMV, further supporting a role for Tsg101 as a positive regulator of Old World arenavirus entry." (PMID 21931550, 2011). "The cells were infected with HCoV-OC43, with N protein serving as an indicator of virus infection, and analyzed for the localization of the endogenous VPS28 and TSG101." (PMID 40407327, 2025). "We found that knockdown of ESCRT-0 subunit HRS or the ESCRT-I subunit TSG101 not only decreased HBV-stimulated lysosomal trafficking of NTCP-EGFP-mCherry, but also largely abolished viral infection in HepG2-NTCP cells." (PMID 39746094, 2025). "Taken together, these results provide evidence that TSG101 is a proviral cellular factor for PRRSV assembly, which will be a promising target to interfere with the viral infection." (PMID 35080428, 2022). "Similar to our results, JEV proliferation does not change the cellular TSG101 expression to promote viral infection." (PMID 35080428, 2022). "Interestingly, our study showed that TSG101 facilitated the viral infection independent of ubiquitin-binding activity (data not shown)." (PMID 35080428, 2022). "To determine whether Tsg101 assists in macropinocytosis of KSHV, we performed a triple colocalization IFA by staining for Tsg101 in the HMVEC-d cells incubated with the macropinocytic marker dextran (Texas Red labeled) in the presence or absence of virus infection for 5, 10 and 30 min." (PMID 27764233, 2016).
papillary thyroid carcinoma (6 papers, 2014 to 2023). "In contrast, the overexpression of the ANXA10 gene significantly inhibits HepG2 cell proliferation in vitro, and its downregulation inhibits papillary thyroid cancer proliferation; it acts directly on TSG101 by inactivating the MAPK/ERK signalling pathway." (PMID 36936694, 2023). "ANXA10 suppresses papillary thyroid carcinoma apoptosis and promotes proliferation by up-regulating TSG101 thereby activating the MAPK/ERK signaling pathway." (PMID 36158697, 2022). "An early study verified that the upregulation of TSG101 might boost carcinogenesis in papillary thyroid carcinoma, followed by a study that proved that its expression might be necessary for processes involved in tumor progression." (PMID 30675171, 2019). "However, upregulation of TSG101 was found in thyroid papillary carcinomas, and breast, ovarian and gastrointestinal tumors, while downregulation of TSG101 was observed in endometrial and cervical cancers." (PMID 24765146, 2014). "Conversely, in papillary thyroid cancer, the knockdown of ANXA10 promotes apoptosis by inhibiting the MAPK/ERK signalling pathway through the downregulation of TSG101." (PMID 36936694, 2023).
AIDS (5 papers, 2010 to 2023). A syndrome resulting from the acquired deficiency of cellular immunity caused by the human immunodeficiency virus (HIV). "Furthermore, specific polymorphisms within the 5’ sequence of TSG101 encoding gene (between the −183 and +181 nucleotides with respect to the translation start codon) have been associated with the acquired immunodeficiency syndrome (AIDS) progression, likely due to an effect on plasma HIV-1 load." (PMID 33668191, 2021). "Variation in TSG101 has been associated with differences in AIDS progression rates, although the SNPs used in that study did not overlap with those used by the current study, so that beneficial or detrimental alleles could not be identified in the Biaka (or other HGDP populations)." (PMID 23217182, 2012). "EVs isolated from serum samples of HIV+ controls and HIV+ pre-AIDS-NHL cohort participants were characterized by quantifying the expression of EV specific markers, CD9 and TSG101, to verify their identity as EVs." (PMID 37809067, 2023).
pancreatic cancer (5 papers, 2014 to 2025). "Dysregulation of TSG101 function has been associated with aberrant exosome secretion, which can facilitate the horizontal transfer of oncogenic factors, microRNAs, and drug resistance mechanisms among pancreatic cancer cells." (PMID 40952239, 2025). "Similar to the characterisation of EVs from human pancreatic cancer cell lines, Alix, TSG101 and CD9 were detected whereas calreticulin and GAPDH were undetected in the P100 fractions from KPC and TPAC cells after ultracentrifugation." (PMID 39863771, 2025). "The accumulation of TSG101‐mediated exosomal cargo has been reported to enhance tumor invasiveness, immune evasion, and chemoresistance in pancreatic cancer." (PMID 40952239, 2025). "In contrast, the expression of exosome-related proteins, such as RAB27A, TSG101 and CD9, increased immediately after radiation in pancreatic cancer cells." (PMID 32228703, 2020). "Among the previously known and here confirmed interactors (CDH1, DISP1, SCFD1, USE1, TSG101, and USP8), CDH1 (E‐cadherin), a critical adhesion molecule, is frequently lost or downregulated in pancreatic cancer, promoting epithelial‐to‐mesenchymal transition (EMT) and enhancing tumor invasiveness." (PMID 40952239, 2025).
bladder cancer (4 papers, 2017 to 2024). "Thus, we isolated sEV from bladder cancer cells by differential centrifugation, and they displayed sphere-like morphology, diameter ~ 100 nm, high expression of CD63, Alix, and TSG101, and low expression of the ER-associated chaperone protein calnexin." (PMID 38561669, 2024). "We selected generic exosome markers CD9, CD63, and TSG101, as well as the EDIL-3 and MUC4 for Western blotting analysis of urinary exosome proteins prepared by UC and NanoPoms methods, with the human bladder carcinoma cell line HTB9 as the control." (PMID 35787656, 2022). "Western blot analysis of EVs isolated from three bladder cancer cell lines showed the presence of the exosome markers Alix, CD9, and TSG101." (PMID 29207636, 2017).
colorectal cancer (4 papers, 2014 to 2023). A primary or metastatic malignant neoplasm that affects the colon or rectum. "High levels of exosomal TSG101 are associated with aggressive phenotypes and the metastasis of colorectal cancers." (PMID 37242707, 2023). "The downregulation of TSG101 decreases the secretion of WNT5B-containing exosomes from colorectal cancer cells." (PMID 37242707, 2023). "In order to further confirm this observation, Western blot analysis was performed for Alix and TSG101 in exosomes isolated from colostrum samples, MM, commercial milk (CM) and LIM1215 colorectal cancer cells." (PMID 28725021, 2017).
gallbladder cancer (4 papers, 2014 to 2024). "The present study indicates that positive TSG101 and PEG10 expression are closely associated with the clinical, pathological and biological behaviors, and a poor prognosis in gallbladder cancer." (PMID 24944680, 2014). "However, no studies have shown the involvement of TSG101 in gallbladder cancer." (PMID 24944680, 2014).
leukemia (4 papers, 2013 to 2025). A malignant (clonal) hematologic disorder, involving hematopoietic stem cells and characterized by the presence of primitive or atypical myeloid or lymphoid cells in the bone marrow and the blood. "Since then, splice variants of TSG101, particularly the major isoform, TSG∆154-1054, have been reported in many cancers, including breast, ovarian, lung, prostate, cervical, liver cancers, and leukemia." (PMID 30759747, 2019).
breast tumor (3 papers, 2016 to 2024). "Additionally, immunofluorescence analysis of breast tumours revealed that BHS synergized with paclitaxel to significantly decrease the expression of TSG101 and CXCL1, indicating that paclitaxel‐induced EV‐Apo biogenesis and CXCL1 secretion were suppressed." (PMID 39051750, 2024).